Y_RNA (Y RNA )
Gene: Miscellaneous RNA gene on chromosome 10 (37,994,863 to 37,994,975, forward strand). Ensembl gene ENSG00000206840.
Homologues: Orthologues: chimpanzee Y_RNA (98% identical). Paralogues in human: RNY1 (88% identical), Y_RNA (88% identical), Y_RNA (87% identical), Y_RNA (86% identical), RNY1P8 (85% identical), Y_RNA (85% identical), Y_RNA (84% identical), RNY1P11 (83% identical), RNY1P7 (83% identical), Y_RNA (83% identical), Y_RNA (82% identical), Y_RNA (81% identical), and 95 more.